GNG14 (G protein subunit gamma 14)
Description:
Guanine nucleotide-binding proteins (G proteins) are involved as a modulator or transducer in various transmembrane signaling systems. The beta and gamma chains are required for the GTPase activity, for replacement of GDP by GTP, and for G protein-effector interaction.
Synonyms: HG3K
Gene: Protein-coding gene on chromosome 19 (12,687,998 to 12,688,422, forward strand). Ensembl gene ENSG00000283980.
Subcellular location: Cell membrane
Gene Ontology:
Molecular function: G-protein beta-subunit binding
Biological process: G protein-coupled receptor signaling pathway
Cellular component: heterotrimeric G-protein complex; plasma membrane
Diseases named in the same sentence as GNG14 in open-access papers:
GNG14 is named in the same sentence as 1 disease in open-access papers, as found by Europe PMC text mining. Sharing a sentence is not in itself a finding about the gene and the disease.
GNG14 shares sentences with these, for which no sentence is quoted: tumours (1 paper).